EPCAM (epithelial cell adhesion molecule)
Diseases named in the same sentence as EPCAM in open-access papers (continued):
Sharing a sentence is not in itself a finding about the gene and the disease.
breast carcinoma (continued). "A proportion of DTC in bone marrow is also positive for EpCAM and their depletion in breast cancer patients has been demonstrated by anti-EpCAM monoclonal antibody edrecolomab." (PMID 17211480, 2007). "As reviewed by W Gillanders (St Louis, USA), EpCAM overexpression on breast cancer cell lines is mandatory for proliferation, migration, and invasiveness of tumour cells." (PMID 17211480, 2007). "Epithelial cell adhesion molecule expression in breast cancer has been previously published for more than 1700 patient samples." (PMID 16404366, 2006). "As models, we used the breast cancer cell lines MCF-7 and BT474 (ATCC HTB-22 and HTB-20), because they express heterogeneous levels of the target antigens HER2/neu and EpCAM comparable to micrometastatic breast cancer cells in vivo." (PMID 15771776, 2005). "The semiautomated CellSearch® platform (Janssen Diagnostics, Raritan, NJ, USA) isolates breast cancer CTCs using ferromagnetic beads coated in EpCAM and defines CTCs according to morphological characteristics, positive expression of cytokeratins and absence of the leukocyte marker CD45." (PMID 41372129, 2025). "Blood exosomes from 30 breast cancer patients, 30 colorectal cancer patients, 30 lung cancer patients, and 39 healthy controls were collected and quantified for PD-L1, EpCAM, and EGFR, showing that the expression of these genes was increased in cancer patients." (PMID 40075875, 2025). "Notably, approximately 70% of CTCs in both metastatic colorectal and breast cancers express the epithelial cell adhesion molecule (EPCAM), members of the Keratin (KRT) family, and/or vimentin (VIM)." (PMID 40565003, 2025). "Next, we tested EpCAM expression in various human breast cancer cell lines." (PMID 40792441, 2025). "This study shows that EpCAM and Trop2, two closely related surface markers of carcinoma, play antagonistic roles, respectively opposing or favouring cohesion and collective migration of breast cancer cells." (PMID 39572744, 2025). "Additionally, in the realm of CAR-T and CAR-NK therapy for breast cancer, several targets, such as EpCAM (NCT02915445), VEGFR (NCT05477927), EGFR, and B7-H3 (NCT05341492), have been explored in clinical trials." (PMID 41573636, 2025). "Since a clinical application of NIR-PIT would be relatively easy for breast cancers, and MCF-7 would be a good model for cancer that can be treated with EpCAM-NIR-PIT but cannot be treated with EGFR-NIR-PIT, we used MCF-7 breast cancer as a model of EpCAM-targeted NIR-PIT in vivo." (PMID 40792441, 2025). "Moreover, there is evidence of heterogeneity, and of prognostic significance, of EpCAM levels themselves in different breast cancer subtypes." (PMID 40411659, 2025). "Single-cell resolution western blotting have identified glyceraldehyde-3-phosphate dehydrogenase, β-microtubulin, pankeratin, extracellular regulated protein kinases, epithelial cell adhesion molecule (EpCAM), ER, eIF6E and other proteins expressed in CTCs derived from breast cancer patients." (PMID 38427120, 2024). "GIV protein was virtually undetectable in lysates from monocultures of 3 different ER+ breast cancer cells but detected as a full-length protein (~250 kDa) in cells recovered with EpCAM-based immunocapture and lysis following 3 days in contact cultures with HS5 cells." (PMID 39480488, 2024). "CAR-NK-92 cells based on CD28-CD3ζ signaling domain have anti-tumor cytotoxicity targeting EpCAM and ErB2 breast cancer cells, EGFR on glioblastoma cells and breast cancer brain metastases, CD19 on B-cell malignancies, CS1 on multiple myeloma cells, and CD33 on acute myeloid leukemia cells." (PMID 39633491, 2024). "Patients with nasopharyngeal carcinoma, breast cancer and other EpCAM positive solid tumors." (PMID 39397869, 2024).
breast carcinoma (continued). "Moreover, EpCAM aptamer-modified Au NPs (Au NPs-EpCAM) can specifically recognize proteins on breast cancer MDA-MB-231 exosomes through the affinity between the aptamer and protein, thus achieving effective tumor screening." (PMID 38667191, 2024). "- The secretion of EpCAM BiTE has been shown to effectively promote activation of T cells.- The VV-EpCAM BiTE demonstrates enhanced antitumor activity in EpCAM-expressing breast cancer.- Both VV-EpCAM BiTE and VV-Ctrl exhibit similar anticancer properties in the EpCAM-negative carcinoma model." (PMID 38464532, 2024). "Similarly, EpCAM upregulation of AKT downstream targets promotes stemness and DNA loss repair in breast cancer cells, thereby enhancing resistance to radiotherapy and DNA-damaging chemotherapeutic agents (such as doxorubicin, cisplatin, or gemcitabine)." (PMID 38791091, 2024). "However, the investigation of these epithelial markers proved ineffective in identifying cell population expressing different combinations of EpCAM and cytokeratin 7/8 with prognostic significance for breast cancer metastases." (PMID 38806508, 2024). "We used two epithelial markers (EpCAM and cytokeratin 7/8) to assess the count of CTCs in 57 breast cancer patients, both with (M0mts) and without metastasis (M0) during the follow-up period, as well as in M1 breast cancer patients." (PMID 38806508, 2024). "Surprisingly, we found CD24+ circulating cells (CCs) in peripheral blood of breast cancer patients which have no epithelial markers (EpCAM and cytokeratin 7/8) but was strongly associated with distant metastasis." (PMID 38806508, 2024). "The experimental results showed that the AAV2MEC1 virus could specifically infect EpCAM-positive breast cancer cells and accurately deliver the suicide gene HSV-TK to tumor tissue in mice, significantly inhibiting tumor growth." (PMID 38082377, 2023). "EpCAM is a transmembrane protein significantly overexpressed in breast cancer tissues." (PMID 40226410, 2023). "The aim of this study is to evaluate an AAV vector that can selectively target breast cancer cells and to investigate its specificity and anti-tumor effects on breast cancer cells both in vitro and in vivo, offering a new therapeutic approach for the treatment of EpCAM-positive breast cancer." (PMID 38082377, 2023). "For example, both tumors were mainly composed of epithelial breast cancer cells (EPCAM+) with a similar distribution of hormone receptors (ERBB2 for HER2, ESR1 for estrogen receptor, and PGR for progesterone receptor) and histology markers (CDH1 for E-cadherin)." (PMID 37301892, 2023). "This PTS-coupled AAV also successfully recognized EpCAM-positive breast cancer cells in vitro." (PMID 38082377, 2023). "In breast cancer, KDM2A can promote DNA methylation by inhibiting the expression of tet-eleven translocation 2 (TET2), thereby suppressing the expression of epithelial cell adhesion molecule (EpCAM) and E-Cadherin, further enhancing the tumor invasion capacity of breast cancer." (PMID 37821959, 2023). "Patients with nasopharyngeal carcinoma or breast cancer have been enrolled in a phase I clinical trial, which investigated the safety and tolerability of epithelial cell adhesion molecule (EpCAM)- specific CAR-T cells, in terms of treatment-related AEs and maximum tolerated dose (MTD)." (PMID 36564524, 2023). "Based on the function of the N-glycan chain of EpCAM in breast cancer cells, it is reasonable to speculate that targeting the N-glycosylation of EpCAM may also have unexpected effects in liver cancer." (PMID 36990999, 2023). "The glycosylation of EpCAM is inhibited, which increases the expression of EpCAM in breast cancer." (PMID 37904877, 2023). "Furthermore, expression of the EPCAM gene, which is overexpressed in breast cancer compared to normal tissue, was also differentially expressed." (PMID 37138793, 2023).
breast carcinoma (continued). "The function of EpCAM-AsiCs in the process of cancer immunity was evaluated in genetically engineered mouse breast cancer models, which indicated that Upf2, Parp1, Cd47, and Mcl1 knockdown by EpCAM-AsiCs obviously inhibited tumor progression and promoted tumor-infiltrating immune cell functions." (PMID 36969696, 2023). "EpCAM low-expressing CTCs may play a particular role in the development of brain metastasis in breast cancer patients." (PMID 36823365, 2023). "Importantly, the gene expression pattern of our EpCAM/CD49f-defined luminal subpopulation was significantly similar to a human luminal breast cancer gene signature (right), further supporting the human relevance of the MMTV-PyMT model." (PMID 36443319, 2022). "This process demonstrated that the EpCAM might possess the capability to induce the EMT in breast cancer to promote multidrug resistance." (PMID 36315446, 2022). "Gene expression profile of blood samples from metastatic breast cancer (61% positivity) and from healthy donors enriched for EpCAM+ cells by the CellSearch® system were performed by RT-qPCR of a panel including 1 epithelial cell-specific and 22 breast-specific genes." (PMID 36428760, 2022). "Trophoblast cell surface antigen 2 (Trop2) is a widely expressed glycoprotein and a member of the epithelial cell adhesion molecule (EpCAM) family in many normal tissues, and overexpressed in a variety of human cancers, including gastric cancer and breast cancer." (PMID 36497465, 2022). "The impact of EpCAM expression on breast cancer prognosis is dependent on intrinsic subtype." (PMID 36546899, 2022). "In addition, we also suggested that deglycosylated EpCAM facilitated cell apoptosis of breast cancer cells via PI3K/Akt signaling pathway." (PMID 34983878, 2022). "Moreover, EpCAM expression is frequently upregulated in a variety of human cancers, including lung cancer, breast cancer, cervical cancer, and pancreatic cancer." (PMID 36077658, 2022). "It has also been shown that ZEB1, a transcription factor associated with epithelial–mesenchymal transition in cancer progression, is not only a direct transcription repressor of E-cadherin in human breast cancer cell line but also of EpCAM in both human pancreatic and breast cancer cell lines." (PMID 35241091, 2022). "In malignant tumors, such as breast cancer (BC), EpCAM was found to be hyperglycosylated." (PMID 36369033, 2022). "EpCAM is a widely used biomarker for tumor cell isolation in both basic studies and clinics, because of its strong upregulation in a variety of human cancers, including lung cancer, breast cancer, cervical cancer, pancreatic cancer, and stomach cancer." (PMID 36077658, 2022). "Taken together, our findings proved that glycosylated EpCAM might regulate the apoptosis by influencing autophagy in breast cancer cells." (PMID 34983878, 2022). "Thus, we were interested in discussing the role of autophagy in deglycosylated EpCAM-mediated apoptosis in breast cancer cells." (PMID 34983878, 2022). "In addition, a phase I study is recruiting patients with breast cancer to evaluate the safety of autologous engineered T cells armed with chimeric antigen receptor (CAR‐T) recognizing EpCAM." (PMID 35762299, 2022). "In addition, for each breast cancer cell line, rare cancer cells were mixed with 106 EpCAM/HER2-negative U937 cells to better mimic CTCs in complicated blood (System 2)." (PMID 36246381, 2022). "Lower levels of EpCAM inhibit cell proliferation in breast cancer cells." (PMID 36428553, 2022). "Therefore, blocking EpCAM on the surface of breast cancer cells can be an approach to inhibit tumor growth, metastasis and improve the therapeutic effects." (PMID 35414783, 2022). "The anti‐EpCAM‐bound surface could selectively capture human breast cancer (MCF‐7) cells at 37°C (above LCST)." (PMID 37324582, 2022).
breast carcinoma (continued). "Furthermore, quercetin also suppresses the self-renewal capability and invasiveness of CSCs in breast cancer by regulating EpCAM expression." (PMID 35204240, 2022). "The endoplasmic reticulum aminopeptidase 2 (ERAP2) has been identified by our group as an EpCAM‐associated protein, and here we continue this effort and present another novel finding that Annexin A2 (ANXA2) is a potential interacting partner of EpCAM in the EpCAM+ ERα+ breast cancer cells." (PMID 34240826, 2022). "However, since the EMT is a critical early event in the invasion and metastasis of breast cancer, many breast cancer patients lack EpCAM + CTC, which impairs CTC separation." (PMID 36217151, 2022). "Therefore, we developed a targeted theranostic biomimetic drug delivery platform using hRBCm-coated anti-EpCAM functionalized Na131I radiolabeled PLGA nanoparticles (EINPs) to treat MCF-7 breast-cancer cells." (PMID 35877345, 2022). "Over all, the finding suggested that glycosylated EpCAM might inhibit the proliferation through influencing autophagy in breast cancer cells." (PMID 34983878, 2022). "The result showed that deglycosylated EpCAM promoted autophagy in breast cancer cells." (PMID 34983878, 2022). "In order to better understand the correlation HER2+/EpCAM, the HER2+ breast cancer DHSF-BR16 cells endowed by a moderate expression of EpCAM, may represent a suitable in vitro tumor model." (PMID 33863935, 2021). "Whether EpCAM directly causes the release of β-catenin from E-cadherin is unknown, but it has been shown that silencing of EpCAM in breast cancer cell lines increased β-catenin binding to the cytoskeleton." (PMID 34209658, 2021). "EpCAM was shown to stimulate AP-1 transcription factor activity in breast cancer cell lines." (PMID 34209658, 2021). "The deglycosylation of EpCAM repressed proliferation of breast cancer cells and fostered apoptosis." (PMID 33889547, 2021). "In breast cancer, EpCAM is highly overexpressed in primary and metastatic lesions." (PMID 34209658, 2021). "Finally, anti-EpCAM was conjugated with HNTs-FITC-ICG-RBCM under the help of streptavidin (SA) to improve the specific uptake of breast cancer cells." (PMID 34361636, 2021). "In breast cancer, multiple studies suggest that EpCAM promotes invasion." (PMID 34209658, 2021). "Furthermore, Rab5c is involved in recycling of integrin beta-1, a potential interactor of EpCAM, which is important for invasiveness of breast cancer cells." (PMID 34693227, 2021). "Furthermore, to confirm our findings, we analyzed the expression of a recognized additional marker for breast cancer stemness, the adhesion molecule EpCAM." (PMID 34315857, 2021). "Similarly, EpCAM expression ranges from 45–100% in different breast carcinomas in human patients and expression can be uniform or heterogeneous in various epithelial tumors." (PMID 33614766, 2021). "In an analysis of patients with ovarian cancer, lung cancer, or stomach cancer, we found that those with high expression of EpCAM shown significantly shorter survival times, suggesting that EpCAM plays a part in the development of breast cancer, ESCA, HNSC, LUAD, LUSC, and stomach adenocarcinoma." (PMID 34790117, 2021). "Importantly, EpCAM is highly expressed in all breast cancer subtypes and thus can serve as a potential NK-CAR target in HR+ tumors." (PMID 34135901, 2021). "Mechanistically, PTEN up-regulates MALAT1 expression by binding and sequestering miR-17, miR-20a and miR-106b, and MALAT1 suppresses colorectal and breast cancer cell migration and invasion by reducing the pro-metastatic Epithelial Cell Adhesion Molecule (EpCAM) and ITGB4." (PMID 32174966, 2020).
breast carcinoma (continued). "In early breast cancer patients, EpCAM+CTCs express both M and stemness-related genes; the overexpression of these markers may be associated with worse prognosis." (PMID 33207810, 2020). "In vitro evaluation was performed using EpCAM-expressing MDA-MB-468 breast cancer cells." (PMID 33066684, 2020). "Similarly, EPCAM silencing in breast cancer cell lines leads to a 35–80% reduction in the rate of cell proliferation." (PMID 32764280, 2020). "CellSearchTM, the only FDA-cleared platform for clinical CTC testing, captures breast cancer CTCs based on the combination of EpCAM+ and cytokeratin+ (epithelial origin), and CD45− (for leukocyte depletion) biomarkers, leading to exclusion of non-epithelial or stem-like CTCs." (PMID 32575420, 2020). "Likewise, while the epithelial cell adhesion molecule (EpCAM) is strongly expressed in breast cancer tissue, it seems to be decreased on serum-derived exosomes of breast cancer patients." (PMID 31100935, 2019). "EpCAM is a known marker of cancer stem cells in pancreatic, liver, colorectal and breast cancers." (PMID 31048929, 2019). "In addition, we followed up 190 breast cancer patients for over 10 years and conducted a survival analysis for the positivity of expression (EpCAM, FADD, and αB-crystallin) or the level of expression (NDRG1) in the primary tumor sites." (PMID 31443698, 2019). "Obviously, EpCAM plays a role in the metastasis of breast cancer cells to the lymph node." (PMID 31443698, 2019). "EPCAM or Epithelia Cell Adhesion Molecule is a type I transmembrane protein that is expressed in the majority of normal epithelial tissues and is overexpressed in most epithelial cancers including breast cancer." (PMID 31646972, 2019). "In addition, a recent publication describes that EpCAM+ cells with stem phenotypes provide prognostic information in early-stage breast cancer patients, reinforcing our findings." (PMID 31817194, 2019). "Recent studies also demonstrated that high EpCAM expression may predict poor clinical outcome in breast cancer, ovarian carcinoma, and hepatocellular carcinoma." (PMID 31324239, 2019). "The level of EpCAM-positive exosomes in these breast cancer patients was significantly increased." (PMID 31514467, 2019). "Further studies using multiparametric flow cytometry have associated EpCAM-negative CTC with a significantly decreased OS in breast cancer patients." (PMID 31636732, 2019). "However, the presence of EpCAM (-) CTCs in the blood circulation has been also reported for patients with breast cancers, colorectal cancer, or non small cell lung cancer." (PMID 31225512, 2019). "Furthermore, our recent published work also investigated the dynamic interconversions observed between the transitional epithelial and mesenchymal subpopulations delineated by EpCAM profiling in the predominantly epithelial PMC42-LA breast cancer cells." (PMID 31430931, 2019). "They found that EVs from breast cancer patients expressed significantly higher level of EpCAM." (PMID 31212643, 2019). "Furthermore, the EpCAM expression rate is quite variable and can reach up to 50% negativity in mammary tumors, being more expressed in advanced tumors." (PMID 31581693, 2019). "Furthermore, an additional marker can be intergration in the CellSearch System such as for example HER2 which allows differentiation of CTC subpopulations of breast cancer (e.g. EpCAM+/HER2− vs. EpCAM+/HER2+)." (PMID 29977481, 2018). "In addition, four cytokeratin genes (KRT8, KRT16, KRT17, and KRT19) and eight tumor-associated genes (TERT, MUC16/M17S2/CA125, CD44, TWIST1, TACSTD1/EpCAM/CD326/ESA/HEA125/GA733, DPP4/CD26, ESR1, and PGR), were upregulated in CRC and breast cancer samples." (PMID 29882767, 2018).